NEFL (neurofilament light chain)
Diseases named in the same sentence as NEFL in open-access papers (continued):
Sharing a sentence is not in itself a finding about the gene and the disease.
spinal muscular atrophy (16 papers, 2014 to 2025). A motor neuron disease that affect the muscles, and characterized by muscle weakness and atrophy resulting from progressive degeneration and irreversible loss of the anterior horn cells in the spinal cord (i.e., lower motor neurons) and the brain stem nuclei. "The aim of this study was to evaluate neurofilament light chain as blood biomarker for disease activity in children and adolescents with different types of spinal muscular atrophy (SMA) and establish pediatric reference values." (PMID 34482646, 2021).
neuroblastoma (14 papers, 2004 to 2023). Neuroblastoma (NB) is the most common solid, extracranial childhood tumor. "We further analysed the expression of differentiation-related genes (SYP, NEFL, ENO2, MAPT) in high-risk neuroblastoma patients and correlated them to HIF1A expression." (PMID 34557995, 2022). "Whether NGFR upregulation is instrumental and causal for the enhanced expression of NTRK2, NEFL, TUBB3, and MAP2 that we observe in the L-AN-5 neuroblastoma system, remains to be investigated." (PMID 33174841, 2020). "In line with previously published analyses of HOXC9 in neuroblastoma cells, we found a significant up-regulation of genes involved in neuronal differentiation pathways such as DNER, NEFL, DBH, TH, RET, MAP2 and NPY." (PMID 25406647, 2014).
proteinopathy (14 papers, 2017 to 2025). "Combinations of seed amplification assays that identify the underlying proteinopathy together with other biomarkers, for example, neurofilament light chain as a measure of neuroaxonal breakdown, have the potential to further improve diagnostic accuracy." (PMID 35813946, 2022).
Guillain-Barre syndrome (13 papers, 2013 to 2024). A spectrum of rare post-infectious neuropathies that usually occur in otherwise healthy patients. "In this retrospective analysis, we show multifaceted associations between serum neurofilament light chain concentrations and outcomes in Guillain-Barré syndrome." (PMID 32183837, 2020).
schizophrenia (13 papers, 2012 to 2025). A major psychotic disorder characterized by abnormalities in the perception or expression of reality. "It has also been observed that patients with ketamine-induced persistent psychosis show elevated levels of neurofilament light chain (NfL), a marker of neuroaxonal damage, higher than those found in patients with schizophrenia, indicating potential neurotoxicity associated with chronic use." (PMID 41369360, 2025).
Sepsis (13 papers, 2018 to 2026). Sepsis is defined as life-threatening organ dysfunction caused by a dysregulated host response to infection. "This is the first study on the relevance of neurofilament heavy (NfH) and neurofilament light chains (NfL) in cerebrospinal fluid (CSF) and plasma to detect SAE and to predict outcome in patients with sepsis." (PMID 30677080, 2019).
demyelinating disease (12 papers, 2016 to 2024). A broad group of disorders that affect the myelin sheaths that cover the neurons. "Serum neurofilament light chain (sNfL) and serum glial fibrillary acidic protein (sGFAP) are new biomarkers that have been shown to have increased values in demyelinating diseases." (PMID 38002031, 2023). "The CNS damage markers neurofilament light chain protein (NfL), total Tau protein (t-Tau) and glial fibrillary acidic protein (GFAP) are constituent parts of neurons and glial cells that have primarily been used in neurological diagnostics for dementia and demyelinating diseases." (PMID 39048548, 2024).
status epilepticus (12 papers, 2018 to 2026). Status epilepticus is defined as a continuous seizure lasting more than 30 min, or two or more seizures without full recovery of consciousness between any of them. "For example, high levels of neurofilament light chain (NfL) in status epilepticus represent a promising biomarker of seizure-related neuronal damage." (PMID 41018203, 2025). "We explored the potential of neurofilament light chain (NfL) in serum and cerebrospinal fluid as a biomarker for neurodestruction in status epilepticus." (PMID 36624182, 2023).
glioblastoma (11 papers, 2012 to 2025). The most malignant astrocytic tumor (WHO grade IV). "In fact, miR-381-3p contributes to temozolomide resistance in glioblastoma cells by targeting NEFL and regulating stemness factors in an NEFL-dependent manner." (PMID 31861937, 2019). "In glioma, overexpression of NEFL significantly suppressed the proliferation and invasion of cancer cells and enhanced the chemosensitivity of glioblastoma cells to temozolomide." (PMID 31057612, 2019). "Overexpression of NEFL significantly suppressed the proliferation and invasion of U251 cells and enhanced the chemosensitivity of glioblastoma cells to TMZ." (PMID 25605243, 2015). "Our data suggested that targeted inhibition of miR-381 enhances the sensitivity of cells to TMZ in glioblastoma by inhibiting stemness factors and that NEFL regulates the expression of stemness factors." (PMID 25605243, 2015). "Our research indicated that either suppressing miR-381 or enhancing NEFL expression sensitizes glioblastoma cells to TMZ by inhibiting stemness factors (ALDH1, CD44, CKIT, KLF4, Nanog, Nestin, and SOX2)." (PMID 25605243, 2015). "First, we analyzed the expression of NEFL in the glioblastoma cell lines U251 and U87." (PMID 25605243, 2015). "Glioblastoma cases belonging to the neural subtype were characterized by the expression of genes well-known as neuron markers such as GABRA1, neurofilament light chain (NEFL), synaptotagmin-1 (SYT1) and solute carrier family 12 member 5 (SLC12A5)." (PMID 33324155, 2020). "NEFL (also known as NF68) has been functionally connected to a ligand of PPAR gamma PGJ2, and participates in the tumorigenesis of glioblastoma." (PMID 30322114, 2018). "To validate the data from bulk mRNA seq, we selected a set of neural and glial‐specific genes (i.e., PAX6, BRN2/POU3F2, NF‐L/NEFL, and GFAP) showing high expression in the GLICO model in comparison to independently cultured glioblastoma spheroids or standard glioblastoma 2D culture." (PMID 36744875, 2023). "Thus, the miR-381-NEFL axis is critical for TMZ resistance in GBM, and targeted inhibition of miR-381 or NEFL restoration may offer a new strategy to overcome chemoresistance of glioblastoma to TMZ treatment." (PMID 25605243, 2015). "We showed that the NEFL protein level was reduced in glioblastoma cells compared to non-tumor brain tissues." (PMID 25605243, 2015).
glioma (11 papers, 2008 to 2024). A benign or malignant brain and spinal cord tumor that arises from glial cells (astrocytes, oligodendrocytes, ependymal cells). "GFAP, NEFL, FABP4 and MMP3 are useful for differential diagnosis and prognosis, and are associated with molecular changes in gliomas." (PMID 38879494, 2024). "Another well-known glioma biomarker is NEFL (Neurofilament light polypeptide) also known as neurofilament light chain, a potential tumor suppressor." (PMID 36959545, 2023). "Neurofilament light polypeptide (NEFL) is also a target of miR‐381 in glioma." (PMID 35014178, 2022). "In addition, overexpression of NEFL increases the chemosensitivity of glioma cells to TMZ treatment by downregulating the multidrug resistance factors ABCG2, ABCC3, and ABCC5, which are ABC transporters and function as xenobiotic transporters." (PMID 33324542, 2020). "We identified 8 plasma proteins which were increased in gliomas vs. meningiomas (GFAP, NEFL, EDDM3B, PROK1, MMP3, CTRL, GP2, SPINT3) and 4 proteins which were decreased in gliomas vs. meningiomas (FABP4, ALDH3A1, IL-12B and OXT)." (PMID 36959545, 2023). "In summary, our present research shows that miR-381 is a good target for glioma therapy, and that targeted inhibition of miR-381 enhances the sensitivity of GBM to temozolomide through the regulation of stemness factors by NEFL." (PMID 25605243, 2015). "For example, among the neurofilament genes (INA, NEFH, NEFM, NEFL) present in cluster C, alphainternexin (INA) was the only one overexpressed in both gliomas with 1p19q codeletion and cortex samples in comparison to gliomas with EGFR amplification." (PMID 18492260, 2008). "Parthenolide induced glioma cells to express neuronal markers NeuN, MAP2, SYP, and NEFL, but not astrocyte or oligodendrocyte markers." (PMID 39595109, 2024).
normal pressure hydrocephalus (11 papers, 2006 to 2025). A form of compensated hydrocephalus characterized clinically by a slowly progressive gait disorder (see gait disorders, neurologic), progressive intellectual decline, and urinary incontinence. "Neurofilaments, especially the neurofilament light chain (NfL), have shown promise as indicators of neuronal damage in a variety of neurological diseases, including hydrocephalus." (PMID 40722587, 2025).
corticobasal syndrome (10 papers, 2018 to 2025). Corticobasal syndrome (CBS) is a rare neurodegenerative disease characterized by multifaceted motor system dysfunctions and cognitive defects such as asymmetric rigidity, bradykinesia, limb apraxia, and visuospatial dysfunction. "In this regard, blood neurofilament light chain (NfL) protein distinguished PD from APD patients including PSP, MSA and corticobasal syndrome with high accuracy, 91% specificity and 82% sensitivity." (PMID 29896099, 2018).
sarcopenia (10 papers, 2021 to 2025). Progressive decline in muscle mass due to aging which results in decreased functional capacity of muscles. "Previous researches have confirmed that biomarkers related to the neuromuscular junction, such as the C-terminal agrin fragment and neurofilament light chain, are linked with sarcopenia and neural health." (PMID 40513379, 2025). "Neurofilament light chains (NF-L) are now used as a blood-biomarker of neuronal damage, and its expression might be altered in sarcopenia." (PMID 37581861, 2023). "Furthermore, circulating biomarkers such as growth differentiation factor-15 (GDF15), C-terminal agrin fragment (CAF), neurofilament light chain (NfL), and inflammatory indices have been investigated for their correlation with muscle mass, strength, and sarcopenia status in COPD patients." (PMID 41450343, 2025).
breast cancer (9 papers, 2012 to 2025). A primary or metastatic malignant neoplasm involving the breast. "We report here the results of two separate non-interventional studies (49 patients), which evaluated blood neurofilament light chain (NfL) as a biomarker of CIPN in breast cancer patients treated with paclitaxel." (PMID 37686492, 2023). "We report here the results of two separate non-interventional studies (49 patients) that evaluated blood neurofilament light chain (NfL) as a biomarker of CIPN in breast cancer patients treated with paclitaxel." (PMID 37686492, 2023). "NEFL mRNA expression levels in primary breast cancer tissues from patients with poor prognoses within five years were lower than in cancer patients with good outcomes." (PMID 22319610, 2012). "Neurofilament, light polypeptide (NEFL) was demonstrated to be ectopically expressed in breast cancer tissues and decreased in lymph node metastases compared to the paired primary breast cancers in our previous study." (PMID 22319610, 2012). "In this study, NEFL mRNA was found had a low predictive power to predict the DFS of late-stage breast cancer patients." (PMID 22319610, 2012). "In conclusion, NEFL mRNA was expressed in breast malignancies, and a decreased expression of NEFL indicated a poor long-term survival in early-stage breast cancer patients." (PMID 22319610, 2012). "Kaplan and Meier survival analysis suggests that low NEFL mRNA levels indicate a short DFS for breast cancer patients." (PMID 22319610, 2012). "Neurofilament light chain (NEFL) was implicated in the gastric cancer and breast cancer." (PMID 36527158, 2022). "NEFL mRNA level, as a potential prognostic factor for early-stage breast cancer, could help oncologists choose individual therapeutic strategies." (PMID 22319610, 2012). "Furthermore, when the survival status of patients with different stages of disease progression was analyzed, NEFL mRNA was found to be a prognostic factor to predict DFS of early-stage breast cancer patients." (PMID 22319610, 2012). "However, NEFL mRNA had a low predictive power to determine the DFS of late-stage breast cancer patients (P>0.05)." (PMID 22319610, 2012). "Moreover, expression levels of NEFL mRNA indicated poor DFS in early-stage breast cancer patients." (PMID 22319610, 2012). "Thus, NEFL mRNA is ectopically expressed in breast malignancies and could be a potential prognostic factor for early-stage breast cancer patients." (PMID 22319610, 2012). "Thus, NEFL mRNA expression level could be a potential prognosis prediction marker in breast cancer patients." (PMID 22319610, 2012). "In a previous study, we demonstrated that ectopic NEFL mRNA expression could be detected in breast cancers and lymph node metastases; NEFL mRNA expression in the lymph node metastases was lower than that found in the paired primary breast cancer tissues." (PMID 22319610, 2012). "NEFL mRNA was not expressed in all of the normal breast tissues (11/11), and lower than it in their paired primary breast cancers (P<0.001)." (PMID 22319610, 2012). "NEFL mRNA level was lower in primary breast cancers with positive lymph nodes than in cancers with negative lymph nodes." (PMID 22319610, 2012).
autoimmune disease (8 papers, 2019 to 2025). A disorder resulting from loss of function or tissue destruction of an organ or multiple organs, arising from humoral or cellular immune responses of the individual to their own tissue constituents. "The levels of neurofilament light chain (NFL) in serum or cerebrospinal fluid (CSF) are thought to reflect neuroaxonal damage and are proposed to have a predictive value concerning outcomes in patients with inflammatory and autoimmune diseases associated with myelitis." (PMID 32423153, 2020). "Neurofilament light chain (NfL) has been identified as a robust serum marker of autoimmune disease, traumatic brain injury, and neurodegenerative insult." (PMID 34885083, 2021).
diabetic neuropathy (8 papers, 2014 to 2025). A chronic, pathological complication associated with diabetes mellitus, where nerve damages are incurred due to diabetic microvascular injury involving small blood vessels that supply these nerves, resulting in peripheral and/or autonomic nerve dysfunction. "Neurofilament light chain has shown promise as a marker of axonal damage, with recent studies demonstrating elevated levels in diabetic neuropathy patients." (PMID 40755599, 2025).
acquired peripheral neuropathies (6 papers, 2021 to 2025). "Neurofilament light chain (NfL) levels have been suggested as reflecting axonal damage in various inflammatory and neurodegenerative disorders, including acquired peripheral neuropathies." (PMID 33617139, 2021).
anemia (6 papers, 2021 to 2026). A reduction in the number of red blood cells, the amount of hemoglobin, and/or the volume of packed red blood cells. "Additionally, there was no information on the causes of anaemia (for example, studies on vitamin B12, folate, erythropoietin levels, or iron) and a neurodegeneration biomarker such as CSF neurofilament light chain or MRI measures of atrophy in this study." (PMID 34794413, 2021).
familial Alzheimer disease (6 papers, 2017 to 2025). A degenerative disease of the brain that causes gradual loss of memory, judgment, and the ability to function socially. "Previous studies demonstrated that plasma neurofilament light chain (NFL) played important predictive roles in disease progression and neurodegeneration in the preclinical phase of familial Alzheimer’s disease (AD)." (PMID 31514172, 2019).
glaucoma (6 papers, 2014 to 2025). Increased pressure in the eyeball due to obstruction of the outflow of aqueous humor. "The purpose of this study was to evaluate the relationship between serum and aqueous humor (AH) neurofilament light chain (NfL) and to determine whether serum NfL is elevated in patients undergoing ocular surgery who have glaucoma compared with those who do not." (PMID 39998458, 2025).
migraine (6 papers, 2021 to 2025). "The aim of this study was to assess axonal and glial damage measuring serum levels of neurofilament light chain (NfL) and glial fibrillary acidic protein (GFAP) in migraine patients." (PMID 40781571, 2025).
neuromyelitis optica spectrum disorder (6 papers, 2019 to 2025). "This study aimed to evaluate the potential utility of glial fibrillary acidic protein (GFAP) and neurofilament light chain (NfL) as biomarkers of disease activity in AQP4-IgG-positive neuromyelitis optica spectrum disorder (NMOSD) and MOG antibody-associated disease (MOGAD)." (PMID 41155859, 2025).
preeclampsia (6 papers, 2018 to 2023). Preeclampsia is a hypertensive disorder of pregnancy that is characterized by new-onset hypertension with proteinuria presenting after 20 weeks of gestation, and depending on mild or severe forms may initially present with severe headache, visual disturbances, and hyperreflexia. "Our group and others have showed that peripheral concentrations of the cerebral biomarkers S100B, neuron specific enolase (NSE), tau protein and neurofilament light chain (NfL) are increased in preeclampsia both before onset, during disease and postpartum." (PMID 33556141, 2021). "Concentrations of both tau and neurofilament light chain are increased in the end of pregnancy in women developing preeclampsia in contrast to healthy pregnancies." (PMID 29719006, 2018). "Plasma concentrations of tau and neurofilament light chain were analyzed in 16 women who eventually developed preeclampsia and 36 controls throughout pregnancy with single molecule array (Simoa) method and compared within and between groups." (PMID 29719006, 2018). "A combined model for preeclampsia with tau, neurofilament light chain, S100B and neuron specific enolase in gestational week 25 displayed an area under the curve of 0.77, in week 28 it was 0.75, in week 33 it was 0.89 and in week 37 it was 0.83." (PMID 29719006, 2018).
alcohol use disorder (5 papers, 2022 to 2025). "This study assessed the effects of repetitive transcranial magnetic stimulation (rTMS) of the left dorsolateral prefrontal cortex (DLPFC) on serum neurofilament light chain (NfL) levels, alcohol consumption, craving, and psychological impairment in participants with alcohol use disorder (AUD)." (PMID 35197833, 2022).
autism (5 papers, 2012 to 2026). Persistent deficits in social interaction and communication and interaction as well as a markedly restricted repertoire of activity and interest as well as repetitive patterns of behavior. "MTX2, NEFL and SLC25A27 showed consistently reduced expression in the ACG, MC and THL of autism patients." (PMID 23116158, 2012). "The genes MTX2, NEFL and SLC25A27showed consistently reduced expression in all the three brain regions (ACG, MC and THL) of autism patients." (PMID 23116158, 2012). "NEFL, SLC25A27 and MTX2 showed reduced expression in all the three brain regions of autism patients." (PMID 23116158, 2012). "Metaxin 2 (MTX2), neurofilament, light polypeptide (NEFL) and solute carrier family 25, member 27 (SLC25A27) showed consistently reduced expression in the ACG, MC and THL of autism patients." (PMID 23116158, 2012).
intracerebral hemorrhage (5 papers, 2023 to 2025). A cerebrovascular disorder characterized by bleeding into one or both cerebral hemispheres including the basal ganglia and the cerebral cortex. "In comparison to healthy controls, who had a mean plasma neurofilament light chain (pNfL) level of 336.6 ± 58.9 pg./mL, patients with intracerebral hemorrhage (ICH) demonstrated significantly elevated pNfL levels, averaging 503.5 ± 98.6 pg./mL (p < 0.001)." (PMID 40371084, 2025).